INS (insulin)
Diseases named in the same sentence as INS in open-access papers (continued):
Sharing a sentence is not in itself a finding about the gene and the disease.
Insulin resistance (continued). "We also observed an interaction effect between insulin resistance and Dex, during which insulin-resistant cells co-treated with Dex at 10 μM exhibited significantly reduced BCKDH phosphorylation, which is indicative of increased BCKDH activity." (PMID 40422898, 2025). "TNF-α is another important inflammatory cytokine, which intensifies insulin resistance in T2DM by impairing insulin signaling through serine phosphorylation." (PMID 41463050, 2025). "Suppression of STK25 abundance did not lead to consistent alterations in fasting blood glucose, plasma insulin, or the homeostasis model assessment score of insulin resistance (HOMA-IR), measured at several time points during the study." (PMID 40024534, 2025). "Serum FABP4 levels are negatively correlated with glucose disposal rate (GDR), a marker of insulin resistance in skeletal muscle, as well as with serum insulin levels." (PMID 40002815, 2025). "Abnormal insulin action is a key factor in common diseases such as type 2 diabetes, obesity and insulin resistance." (PMID 40969373, 2025). "Another cytokine, IL-1β, which is elevated in individuals who are sleep-deprived, impairs glucose-stimulated insulin secretion from pancreatic β-cells and induces insulin resistance in peripheral tissues." (PMID 39860000, 2025). "Reduced responsiveness of target tissues (liver, skeletal muscle, and adipocytes) to normal circulating levels of insulin, followed by a gradual decrease in pancreatic insulin production, are the hallmarks of insulin resistance." (PMID 39940428, 2025). "Inducing inflammation, on the other hand, affects the insulin signaling pathways, thereby promoting insulin resistance." (PMID 40563287, 2025). "Insulin resistance (IR) refers to reduced insulin efficiency in promoting glucose intake and utilization." (PMID 41573199, 2025). "WC, insulin resistance, and β-cell function were assessed using fasting insulin level, HOMA-IR, and HOMA-β." (PMID 41302993, 2025). "Flavonoids alleviate insulin resistance and improve insulin signaling by inhibiting inflammatory signaling pathways." (PMID 40740995, 2025). "Modern diets high in refined carbohydrates and sugars and sedentary lifestyles contribute to increased insulin levels and insulin resistance." (PMID 40933557, 2025). "Compared with HFD, MILK reduced homeostatic assessment of insulin resistance along with increased hepatic insulin signaling and decreased hepatic gluconeogenic enzymes." (PMID 40507838, 2025). "Insulin resistance impairs the ability of insulin to promote glucose uptake in tissues, leading to hyperglycemia." (PMID 40093747, 2025). "Hypomagnesemia alters the activity of pancreatic β-cells and modifies insulin secretion, while also promoting insulin resistance through the modulation of insulin receptor autophosphorylation." (PMID 40650304, 2025). "Research has also observed correlations between changes in ghrelin and changes in leptin, adiponectin, insulin, and insulin resistance, which are consistent with the expected direction of weight loss." (PMID 39917742, 2025). "The improvement in insulin resistance in the dexamethasone model, a validated paradigm for testing insulin sensitizers, reinforces the pharmacological relevance of LASSBio-2129." (PMID 41155701, 2025). "The results of the blood tests we performed were as follows: fasting hyperglycemia and fasting insulin resistance were confirmed, with normal blood glucose and insulin response to glucose load; androgens, prolactin and cortisol levels were normal." (PMID 40710038, 2025). "In type 1 diabetes, this is driven by reduced blood insulin content; in type 2 diabetes, it results from insulin resistance." (PMID 40806520, 2025). "Type 2 diabetes is a complex and multifactorial disease characterized by impaired insulin secretion and insulin resistance." (PMID 41009753, 2025).
Insulin resistance (continued). "In spite of the presence of insulin in the blood, insulin resistance prevents the entry of glucose into adipocytes and myocytes due to the deficiency of insulin-dependent glucose transporter GLUT-4 on the cell membrane." (PMID 41141170, 2025). "activation of AMPK signaling indirectly increases the expression of GLUT4 to increase glucose uptake and improves IR, and FGF21 inhibits mTOR signaling to ameliorate insulin resistance due to impaired insulin signaling." (PMID 40881124, 2025). "He-US also reduced insulin levels (~32%), insulin resistance (~53%), and free fatty acids (~52%), while He-M improved hepatic steatosis and reduced liver triglycerides (~26%)." (PMID 41304900, 2025). "This review aims to elucidate the significant applications of iPSC-derived insulin target cells in studying the pathogenesis of insulin resistance and T2D." (PMID 40801620, 2025). "Increased angiotensin II levels and AT1 receptor activity have been shown to decrease adiponectin production, promote oxidative stress, and impair insulin signalling, thereby exacerbating insulin resistance and glucose intolerance." (PMID 40564980, 2025). "In most healthy pregnancies, pancreatic β-cells adapt by increasing insulin secretion to compensate for pregnancy-induced insulin resistance." (PMID 40076938, 2025). "The only variable significantly different between women with insulin resistance and women with normal insulin sensitivity was BMI (29.9 + 2.9 vs. 23.3 + 3.7, respectively, p < 0.05)." (PMID 40507609, 2025). "Calcineurin inhibitors (CNIs), a cornerstone of immunosuppression in kidney transplant recipients, are well documented to impair pancreatic β-cell insulin secretion and exacerbate insulin resistance." (PMID 40492760, 2025). "Specifically, AKI patients exhibit enhanced insulin resistance due to renal glycogen depletion and decreased insulin and glucagon clearance, resulting in hyperglycemia and elevated insulin levels, which serve as critical indicators of disease severity." (PMID 41356816, 2025). "Curcumin can significantly reduce body mass index (BMI), fasting blood glucose, insulin levels, and the degree of insulin resistance." (PMID 40842497, 2025). "This, in turn, affects insulin signalling and is conducive to severe insulin resistance in the placentas of women with GDM." (PMID 39861104, 2025). "In periodontitis, TNF-α outnumbers the insulin molecule binding to the INS-R, thereby inhibiting insulin’s ability to activate the receptor and initiating glucose uptake, resulting in a state of insulin resistance." (PMID 40136728, 2025). "Insulin resistance, a defining feature of type 2 diabetes and metabolic syndrome, is characterized by the body’s reduced ability to utilize insulin effectively, resulting in hyperinsulinemia and a series of metabolic disturbances." (PMID 40564010, 2025). "In contrast, IRS-2 KO mice exhibit insulin resistance in target tissues, such as the muscles and liver, and reduced pancreatic insulin secretion, leading to type 2 diabetes and obesity." (PMID 39859555, 2025). "Under conditions of insulin resistance, liver cells exhibit reduced responsiveness to insulin, resulting in an inability to effectively inhibit fatty acid synthesis and the regular promotion of fatty acid oxidation." (PMID 41050396, 2025). "T2DM is usually due to inadequate insulin production and peripheral (happens in fat, liver, and muscle cells) insulin resistance with compensatory β cell expansion and hyperinsulinemia." (PMID 39996055, 2025). "Early detection of insulin resistance or impaired insulin secretion, even before hyperglycemia, permits timely interventions, such as lifestyle modifications or pharmacological treatments, that can effectively delay or prevent the onset of CFRD." (PMID 41300682, 2025). "Insulin resistance is a very frequent condition in which the resulting effect on the carbohydrate metabolism of a given amount of insulin is inadequate for glucose homeostasis." (PMID 41463109, 2025).
Insulin resistance (continued). "Insulin resistance, characterized by diminished efficiency of insulin in lowering blood glucose within the body, is one of the fundamental mechanisms underlying the pathogenesis of type 2 diabetes mellitus (T2DM)." (PMID 41377946, 2025). "For example, ApoM/S1P exerts protective effects against insulin resistance by activating insulin signaling pathways, such as AKT and AMPK pathways, to enhance mitochondrial function." (PMID 39935473, 2025). "Frequent SSB consumption induces sharp fluctuations in blood glucose and insulin levels, promoting fat deposition and insulin resistance." (PMID 41256920, 2025). "Our previous studies have shown that the deletion of IPMK reduced the activity of insulin signaling in hepatocytes and exacerbated high fat-induced insulin resistance in mice." (PMID 40141045, 2025). "The IRS/Akt pathway is a critical insulin signaling cascade, and suppression of its phosphorylation typically indicates aggravated insulin resistance." (PMID 41480360, 2025). "Different from T2DM, which occurs due to insulin resistance and shares a close link with metabolic syndrome, T1DM is caused by the autoimmune destruction of insulin-secreting pancreatic islet beta cells." (PMID 39847072, 2025). "The pathogenic link between PsA and T2DM is not yet fully understood, but inflammatory cytokines, particularly TNF and IL-17, are known to impair insulin signaling and promote insulin resistance." (PMID 41266905, 2025). "Mice fed a high-fat diet exhibit obesity-related systemic insulin resistance and elevated circulating IL-6 levels, while blockade of excessive IL-6 signaling improves systemic insulin sensitivity illustrated by upregulated skeletal muscle glucose uptake." (PMID 40171198, 2025). "Insulin resistance promotes hepatic lipid accumulation by impairing insulin-mediated suppression of lipolysis and promoting de novo lipogenesis, contributing to the development and progression of MASLD." (PMID 41183221, 2025). "Insulin resistance, defined as the impaired ability of endogenous or exogenous insulin to stimulate glucose uptake, plays a central role in the development of T2DM as part of the broader metabolic syndrome." (PMID 41370222, 2025). "Insulin resistance (IR) is a prevalent metabolic condition characterized by reduced cellular responsiveness to insulin and consequent hyperinsulinemia, and it is a key component of type 2 diabetes and metabolic syndrome." (PMID 41002547, 2025). "Tools such as HOMA2-IR offer validated means to estimate insulin resistance using fasting glucose and insulin concentrations, enabling deeper metabolic phenotyping in at-risk yet undiagnosed populations." (PMID 41481581, 2025). "In this study, exenatide induces Ceacam1 expression and improves insulin clearance, insulin resistance, and liver fat accumulation in high-fat diet-fed mice." (PMID 40699685, 2025). "Compounds that demonstrated the most pronounced activity were selected for extended pharmacological evaluation using oral glucose tolerance test, adrenaline test, and rapid insulin tests in rats with dexamethasone-induced insulin resistance." (PMID 41048431, 2025). "The heterogeneity of T2DM is mainly due to both defective insulin secretion and peripheral insulin resistance." (PMID 41302503, 2025). "Hyperglycemia, abnormal blood insulin levels, and insulin resistance are the main symptoms of type 2 diabetes." (PMID 40806520, 2025). "Reduction of insulin resistance and glycaemic values: Adding insulin-sensitizing drugs or other glucose-lowering drugs with an effect on weight control must be considered." (PMID 38778593, 2025). "Insulin resistance manifests itself as a reduced ability of peripheral tissues (skeletal muscle, liver and adipose tissue) to respond to insulin." (PMID 40892247, 2025).
Insulin resistance (continued). "Therapeutic interventions demonstrated enhanced ISI concomitant with reduced HOMA-IR values relative to model controls, indicating that GSP significantly improved insulin resistance and promoted insulin utilization in T2D rats." (PMID 41376068, 2025). "Research shows that acute exposure to GCs can reduce the ability of adipocytes and hepatocytes to bind insulin, leading to insulin resistance." (PMID 40067840, 2025). "Insulin resistance reduces cells’ responsiveness to insulin, leading to chronic hyperglycemia and metabolic dysregulation in T2D." (PMID 39959358, 2025). "Insulin resistance is characterized by decreased insulin sensitivity and impaired glucose uptake and utilization in tissue cells as core pathological features, and it is a key link in the progression of T2DM." (PMID 41573745, 2025). "In insulin resistance, the adaptive response to exercise training induces an improvement in glucose tolerance and enhanced sensitivity of skeletal muscle insulin to glucose transport." (PMID 41347064, 2025). "Insulin resistance, a condition where cells fail to respond to insulin effectively, has significant health implications." (PMID 40282189, 2025). "Cluster A (blue group) comprised parameters linked to insulin resistance and cardiovascular risk, including CHOL, LDL-C, AIP, TG, HOMA-IR, insulin, PBG, HbA1c, and FBG." (PMID 40428900, 2025). "In this study, the homeostasis model of insulin resistance (HOMA-IR), as a marker of insulin resistance (IR), has been assessed according to fasting blood glucose and insulin levels." (PMID 41011162, 2025). "This impairs insulin signaling and increases hepatic glucose production, perpetuating a cycle of hyperinsulinemia and insulin resistance." (PMID 40868096, 2025). "Nigragenon O was found to promote adiponectin secretion in insulin-resistant 3T3-L1 cells, resulting in decreased blood glucose levels and improved insulin resistance." (PMID 40298635, 2025). "In most cases, both insulin resistance and impaired insulin secretion contribute to the metabolic disturbances affecting carbohydrate, protein, and lipid metabolism." (PMID 40077747, 2025). "This dietary pattern attenuates chronic inflammation via dual pathways: enhancing insulin sensitivity while mitigating insulin resistance." (PMID 40181944, 2025). "GGE03 also improved serum metabolic markers, including glucose, triglycerides, cholesterol, and insulin levels, while reducing insulin resistance and improving insulin sensitivity." (PMID 41009518, 2025). "The development of adipose tissue insulin resistance (AT-IR) involves a complex interplay of endoplasmic reticulum (ER) stress, mitochondrial dysfunction, and inflammation, which converge to disrupt insulin signaling." (PMID 41153663, 2025). "In a study involving 3,148 subjects, it was found that higher levels of FT4 were associated with higher levels of HDL cholesterol and lower levels of waist circumference, insulin resistance, and insulin." (PMID 40444230, 2025). "GP treatment enhanced the expression of JAK2-INSR-IRS2 and Akt in the liver, thereby promoting hepatic insulin signaling and alleviating hepatic glucose production and insulin resistance." (PMID 40869401, 2025). "OLZ has been associated with postprandial elevations in insulin, glucagon-like peptide 1 (GLP-1), and glucagon, consistent with insulin resistance." (PMID 41160558, 2025). "Insulin resistance is a precursor pathological condition of many metabolic diseases, and it is a condition of the decreased responsiveness of insulin-targeting tissues (liver, adipose tissues, and skeletal muscles) to physiological insulin levels." (PMID 39859066, 2025). "The combination of psychological and physical stressors induced marked disturbances in glucose–insulin homeostasis consistent with insulin resistance and metabolic stress." (PMID 41441181, 2025). "Since FGF-21 levels are correlated with adipose tissue mass, plasma glucose and insulin levels (insulin resistance)." (PMID 41341131, 2025).
Insulin resistance (continued). "Tacrolimus has been found to impair insulin secretion from pancreatic beta cells and increase insulin resistance, leading to a disruption in glucose metabolism." (PMID 41009752, 2025). "This suggests a more efficient utilization of insulin by tissues and a significant reduction in tissue-level insulin resistance, leading to better glucose control." (PMID 41394924, 2025). "A hallmark of insulin resistance is the selective impairment of the PI3K pathway, leading to decreased processes such as NO-mediated vasodilation, while insulin continues to activate MAPK-dependent pathways that contribute to atherothrombosis." (PMID 40725728, 2025). "T2DM is a chronic inflammatory disease characterized by insulin resistance and/or insufficient insulin secretion, mainly due to impaired pancreatic β-cell function." (PMID 40284176, 2025). "Type 2 diabetes mellitus (T2DM) is characterized by insulin resistance and impaired insulin secretion from pancreatic beta cells." (PMID 40672421, 2025). "Due to the side effects of oral hypoglycemic drugs and a weak effect on blood glucose control, the long-term insulin treatment can lead to insulin resistance, making the treatment of T2DM challenging." (PMID 39912972, 2025). "Insulin resistance is defined as a reduced biological response of target cells to insulin, despite normal or even elevated circulating levels of the hormone." (PMID 41257477, 2025). "Insulin resistance is defined as a condition of decreased insulin sensitivity in the liver, skeletal muscles, and adipose tissues." (PMID 39859066, 2025). "This regulatory network is further supported by in vivo studies demonstrating that Cav-1 knockout mice exhibit pronounced insulin resistance, whereas Cav-1 upregulation enhances insulin signaling and insulin-induced glucose uptake." (PMID 40243482, 2025). "Insulin resistance is defined as an impairment in insulin signaling pathway and a reduction of GLUT4 and finally a decrease in glucose uptake." (PMID 40656624, 2025). "In animals, QCT can promote insulin secretion, decrease insulin resistance, inhibit inflammation and oxidative stress, and reduce liver fat accumulation." (PMID 39576482, 2025). "When metabolic stress exceeds adaptive capacity, beta cells lose the ability to secrete sufficient insulin for the level of insulin resistance." (PMID 41373704, 2025). "During pregnancy, as insulin resistance intensifies due to placental hormones (human placental lactogen, estrogen, and progesterone), the inability of β-cells to sufficiently augment insulin secretion leads to GDM." (PMID 40076938, 2025). "Insulin resistance (IR) refers to a condition in which the target tissue fails to exhibit a normal coordinated response to normal levels of plasma insulin." (PMID 40441206, 2025). "Despite this, the patient had many clinically meaningful improvements including a 69% decrease in insulin-resistance (HOMA-IR), 41% decrease in C-peptide, and a 64% decrease in fasting insulin, despite minimal weight loss." (PMID 41356674, 2025). "In summary, FGF21 can improve insulin resistance by improving insulin signaling and affecting its downstream pathway." (PMID 40881124, 2025). "Natural products have shown potential in improving insulin sensitivity, reducing insulin resistance, and promoting vasodilation." (PMID 40573277, 2025). "In fact, the liver–pancreas crosstalk is essential in glucose and lipid metabolism and in the development of insulin resistance and type 2 diabetes, with insulin and glucagon playing opposite roles." (PMID 40387904, 2025). "They enhance insulin secretion, improve insulin sensitivity, and mitigate insulin resistance, key factors in the pathophysiology of HTN." (PMID 41340133, 2025). "In women, serum SHBG was further responsible for 19 % (p < 0.001) of the variation in insulin sensitivity, with low SHBG being associated with insulin resistance." (PMID 40532849, 2025).